ITPR1 (inositol 1,4,5-trisphosphate receptor type 1)
Diseases named in the same sentence as ITPR1 in open-access papers (continued):
Sharing a sentence is not in itself a finding about the gene and the disease.
breast carcinoma (continued). "And used the ROC plotter database to predict the response of ITPR1 to chemotherapy, endocrine therapy and anti-HER2 therapy in patients with breast cancer." (PMID 35313846, 2022). "The results showed that the expression of ITPR1 decreased with the increase of SBR grade and NPI grade of breast cancer patients (P < 0.0001)." (PMID 35313846, 2022). "Another eight ARGs (BCL2, BIRC5, EIF4EBP1, ERO1L, FOS, GAPDH, ITPR1, and VEGFA) were explored, and the author found that these genes not only were significantly associated with overall survival but also could predict distant metastasis-free survival in breast cancer." (PMID 34869345, 2021). "Recently, on the basis of the GEO database, Gu and his colleagues constructed an ARG model consisting of eight genes (BCL2, BIRC5, EIF4EBP1, ERO1L, FOS, GAPDH, ITPR1, and VEGFA), which can be used as an independent prognostic indicator of breast cancer." (PMID 32649310, 2020). "The result was validated using breast cancer specimens in the HMUCC cohort; moreover, EGOT expression was also positively correlated with ITPR1 protein expression in the HMUCC cohort." (PMID 30999914, 2019). "In our previous breast cancer-focused lncRNA study, we identified BRRIAR, an unannotated, spliced, antisense lncRNA located within introns of ITPR1 at 3p26 with unknown function." (PMID 41501810, 2026). "ITPR1 was also significantly down-regulated in breast cancer tissues compared with non-cancerous tissues." (PMID 35580861, 2022). "In addition, Ai-lncRNA EGOT can recruit hnRNPH1 to enhance the AS of pre-ITPR1 and form pre-ITPR1/EGOT double-stranded RNA to upregulate the expression of ITPR1, leading to the sensitivity of breast cancer cells to paclitaxel toxicity." (PMID 34750493, 2022). "The analysis of 145 cases of breast cancer and 30 cases of adjacent normal tissues from the Harbin Medical University Cancer Center (HMUCC) further verified the low expression of ITPR1 in breast cancer (Show the comparison between normal breast tissue and HER2 positive tissue)." (PMID 35313846, 2022). "And the increased expression of ITPR1 mRNA was closely related to longer overall survival (OS), distant metastasis free survival (DMFS), disease specific survival (DSS) and relapse free survival (RFS) in breast cancer." (PMID 35313846, 2022). "The expression of ITPR1 in SBR grade and NPI gradually decreases, and the expression of ER positive, HER2 negative, lymph node negative, non-triple negative and non-basal-like states was significantly increased, and it was related to the prognosis of breast cancer." (PMID 35313846, 2022). "In addition, the ITPR1 of patients with triple-negative and basal breast cancer was significantly lower than that of patients with non-triple-negative and non-basal breast cancer (P < 0.0001)." (PMID 35313846, 2022). "The expression of ITPR1 in breast cancer tissue was down-regulated compared with normal tissue." (PMID 35313846, 2022). "Consistently, breast cancer tissues with higher EGOT levels showed higher ITPR1 and LC3B levels in the HMUCC cohort, suggesting that the increased expression of EGOT may force a connection with the autophagic pathway via ITPR1." (PMID 30999914, 2019). "In this study, it was found that the expression of ITPR1 was related to the multiple levels of immune infiltration in triple-negative breast cancer, but is not related to luminal and HER2 breast cancer." (PMID 35313846, 2022). "Expression levels of OXTR, FOS, ITPR1, RCAN1, CAMK2D, CACNA2D and lnc_ZFP161 were significantly down-regulated in the breast cancer tissues compared with nearby non-cancerous tissues." (PMID 33742056, 2021). "We identified down-regulation of OXTR, FOS, ITPR1, RCAN1, CAMK2D, CACNA2D and lnc_ZFP161, and up-regulation of lnc_MTX2 in the breast cancer tissues compared with nearby non-cancerous tissues." (PMID 33742056, 2021).
breast carcinoma (continued). "Expression levels of OXTR, FOS, ITPR1, RCAN1, CAMK2D, CACNA2D and lnc_ZFP161 were significantly down-regulated in breast cancer tissues compared with nearby non-cancerous tissues." (PMID 33742056, 2021).
Gillespie syndrome (22 papers, 2016 to 2024). "In FIN23-3, a candidate de novo variant [p.(Lys181Glu)] in 1,4,5-triphosphate receptor, type 2 (ITRP2) was identified in the sample from the patient, who has a phenotype resembling Gillespie syndrome caused by both AD and AR variants in ITPR1 (OMIM # 147265)." (PMID 33710394, 2021). "A closer look at the phenotype suggests that the clinical features resemble more Gillespie syndrome caused by both AD and AR variants in the paralog gene ITPR1 (OMIM # 147265)." (PMID 33710394, 2021). "Since this publication, the Gillespie syndrome cases in this cohort have been shown to have ITPR1 mutations." (PMID 30242502, 2019). "ITPR1 mutations in Gillespie syndrome are varied, and often involve partial expression of the wild-type gene accompanied by truncated variants that exert dominant-negative effects." (PMID 31658749, 2019). "For patients with a Gillespie syndrome-like iris, the two known genetic causes are ITPR1 and ACTA2 p.Arg179 substitutions." (PMID 30242502, 2019). "This new case of Gillespie syndrome was found to carry the recurrent heterozygous ITPR1 pathogenic variant c.7786_7788delAAG p.(Lys2596del), which has been reported in seven other cases." (PMID 30249237, 2018). "So far, there have been 16 mutations in ITPR1 associated with autosomal dominant cerebellar ataxia and 5 with dominantly inherited Gillespie syndrome." (PMID 29186133, 2017). "Pathogenic missense variants in ITPR1 cause congenital spinocerebellar ataxia type 29 (SCA29), Gillespie syndrome (GLSP), and severe pontine/cerebellar hypoplasia." (PMID 37964426, 2024). "In case of the gene encoding IP3R type 1 (IP3R1, encoded by ITPR1), loss-of-function mutations result in spinocerebellar ataxia types 15 and 29 (SCA15 and SCA29, respectively), Gillespie syndrome, and sporadic infantile-onset cerebellar ataxia." (PMID 35406743, 2022). "Pathogenic variants in the ITPR1 gene are associated with different types of autosomal dominant spinocerebellar ataxia: SCA15 (adult onset), SCA29 (early-onset), and Gillespie syndrome." (PMID 35743164, 2022). "ITPR1 has been widely studied in the nervous system, and linked to human spinocerebellar ataxia 15 (MIM 606658), Gillespie syndrome (MIM 206700), and spinocerebellar ataxia 29 (MIM 117360)." (PMID 33747042, 2021). "Using this approach, each of the Gillespie syndrome case subjects in DDD was found to carry a single plausible pathogenic variant, which was a de novo protein-altering mutation in ITPR1 (MIM: 147265)." (PMID 27108798, 2016). "No plausible disease-causing mutations were identified, suggesting that ITPR1 mutations are specific for iris hypoplasia associated with Gillespie syndrome and that this locus does not contribute to other forms of aniridia." (PMID 27108798, 2016). "The mechanisms underlying the specificity of aniridia in Gillespie syndrome remain unknown, and mice with ITPR1 mutations do not exhibit aniridia." (PMID 31658749, 2019). "Thus, all 13 affected individuals with a clinical diagnosis of Gillespie syndrome that were available to us for study were found to have ultra-rare protein-altering variations affecting only three residues in ITPR1, with at least ten of these mutations having occurred de novo." (PMID 27108798, 2016).
spinocerebellar ataxia type 15 (10 papers, 2012 to 2025). "Deletions of brain-critical exons pointed to the ITPR1 deletion, which has been reported to be associated with spinocerebellar ataxia type 16." (PMID 30148849, 2018). "Interestingly, mutations in Itpr1 have been associated with another movement disorder; spinocerebellar ataxia type 15." (PMID 28283027, 2017). "Spinocerebellar ataxia 15 (SCA15) is an adult‐onset autosomal dominant cerebellar ataxia, primarily caused by deletions in the inositol 1,4,5 triphosphate receptor type 1 (ITPR1) gene." (PMID 41325768, 2025).
Huntington disease (9 papers, 2012 to 2024). Huntington disease (HD) is a rare neurodegenerative disorder of the central nervous system characterized by unwanted choreatic movements, behavioral and psychiatric disturbances and dementia. "To date, genetic mutations in the ITPR1 gene with a pathological relevance in human Huntington’s Disease (HD) and Alzheimer’s Disease (AD) have not been detected." (PMID 32290556, 2020). "We also found many differentially expressed genes related to the Huntington disease (HD) pathway in both areas of the MPS II mouse model; among these, Bbc3, Bdnf, Crebbp, Dctn1, Dlg4, Gpx1, Grin1, Grin2b, Itpr1, and Pparg are up-regulated, while Dnaic2, Dnali1, Hap1, and Vdac2 are down-regulated." (PMID 28513549, 2017).
renal carcinoma (9 papers, 2016 to 2024). A carcinoma arising from the epithelium of the renal parenchyma or the renal pelvis. "in vivo studies have previously indicated that ITPR1 targeting in cancer cells in combination with NK depletion contributed to tumor growth, indicating its role in the regulation of in vivo susceptibility of renal carcinoma cells to NK activities." (PMID 32869505, 2020). "It has been found that ITPR1 protects renal cancer cells against the action of natural killer cells by inducing autophagy." (PMID 39337353, 2024). "Then, ITPR1 was considered prominent in regulating renal cancer cell resistance to NK-mediated lysis." (PMID 35580861, 2022). "Silencing ITPR1 in renal cancer cells inhibited NK-induced Autophagy and vice versa in vivo, And ITPR1 is involved in regulating intracellular calcium signaling and the regulation of Autophagy." (PMID 35580861, 2022). "Recently, ITPR1, the gene encoding IP3R1, has been implicated as a major resistance mechanism of renal carcinoma cells against the lytic action of NK cells by activating autophagy." (PMID 28725634, 2017). "Strikingly, ITPR1 appeared to be one of the most important target genes of HIF2α in a renal carcinoma cell line with dysfunctional pVHL gene and it conferred resistance against NK-induced lysis." (PMID 28725634, 2017). "Of potential interest in this context, ITPR1 has been reported to protect renal cancer cells from NK-mediated lysis." (PMID 27776522, 2016). "This study could provide insight into the connection between HIF2α/ITPR1 axis and NK cells in regulating renal cancer cells." (PMID 38072953, 2023). "Typically, ITPR1 as an autophagy sensor is downregulated in KIRC tumors, but has been reported to protect renal carcinoma cells from NK-mediated killing." (PMID 36588677, 2022). "ITPR1 serves as a direct target of EPAS1 and an autophagy regulator to protect renal carcinoma cells against NK-mediated killing." (PMID 34621314, 2021).
spinocerebellar ataxia type 29 (9 papers, 2012 to 2024). "In summary, our study demonstrates that missense mutations in ITPR1 cause AD congenital nonprogressive spinocerebellar ataxia (SCA29) and further emphasizes the importance of the ITPR1-dependent pathway in the development and maintenance of the normal functions of cerebellum." (PMID 22986007, 2012). "Mutations in inositol 1,4,5-trisphosphate receptor type 1 (ITPR1), an ER calcium channel, have been identified in early-onset, nonprogressive, mild spinocerebellar ataxia type 29 (SCA29, OMIM #117360)." (PMID 39352758, 2024).
neuroblastoma (8 papers, 2013 to 2024). Neuroblastoma (NB) is the most common solid, extracranial childhood tumor. "Expression of ITPR1 and ITPR3 transcripts was as well deregulated in SH-SY5Y neuroblastoma cells upon treatment with CDDP or TOPO this effect was also observed for both treatments in IMR-32 cells and for CDDP treatment in NLF cells." (PMID 28206967, 2017).
prostate carcinoma (8 papers, 2015 to 2023). A carcinoma that arises from epithelial cells of the prostate gland. "ITPR1 has been shown to be expressed in a broad variety of tumours (partly ectopically), particularly in Hodgkin disease (HD) and malignant lymphoid and myeloid cell lines, but also lung cancer, melanoma, prostate cancer and many other tumour entities." (PMID 27776522, 2016). "ITPR1 and GABBR2 may be associated with AD, and prostate cancer." (PMID 36506318, 2022). "ITPR1 although not frequently mentioned in prostate cancer, directly affects the process of apoptosis in colorectal cancer and ovarian cancer." (PMID 37349324, 2023).
Cerebellar atrophy (7 papers, 2009 to 2024). Cerebellar atrophy is defined as a cerebellum with initially normal structures, in a posterior fossa with normal size, which displays enlarged fissures (interfolial spaces) in comparison to the foliae secondary to loss of tissue. "We aimed to identify novel SCA29 and GLSP cases to define core phenotypes, describe the spectrum of missense variation across ITPR1, standardize the ITPR1 variant nomenclature, and investigate disease progression in relation to cerebellar atrophy." (PMID 37964426, 2024). "Considering all ITPR1 mutated patients, a characteristic pattern of superior vermian and cerebellar atrophy was present in 83%, while in the remaining cases (3/18, 17%) a less peculiar diffuse cerebellar atrophy was noted." (PMID 35743164, 2022). "We included both patients previously diagnosed with a pathogenic or likely pathogenic ITPR1 variant as well as patients who were directed to ITPR1 genetic testing due to the presence of isolated superior vermian and hemispheric cerebellar atrophy." (PMID 35743164, 2022). "Mutations in ITPR1 have been linked with cerebellar atrophy on brain imaging, smaller head circumference, and a spectrum of cerebellar disorders." (PMID 32407400, 2020). "Furthermore, cerebellar atrophy was recently highlighted as a hallmark of ITPR1‐related disease, but concordance between cerebellar atrophy and symptom progression is unclear." (PMID 37964426, 2024). "However, recent publications have provided evidence that superior vermian and/or hemispheric cerebellar atrophy may represent a hallmark of ITPR1‐related disorders." (PMID 37964426, 2024). "Considering the whole cohort, a distinctive neuroradiological pattern consisting in superior vermian and hemispheric cerebellar atrophy was identified in 83% patients with causative ITPR1 variants, suggesting this MRI finding could represent a hallmark for ITPR1-related disorders." (PMID 35743164, 2022). "According to available studies, brain magnetic resonance imaging (MRI) of ITPR1-related disorders is characterized by cerebellar atrophy as the main finding." (PMID 35743164, 2022). "In conclusion, through a careful review of MRI images, we demonstrated a peculiar pattern of cerebellar atrophy in patients with ITPR1 gene defects and we propose that it is highly suggestive for the diagnosis, which might orient the choice of genetic testing." (PMID 35743164, 2022).
autosomal dominant cerebellar ataxia (6 papers, 2016 to 2025). A clinically and genetically heterogeneous group of neurodegenerative diseases characterized by a slowly progressive ataxia of gait, stance and limbs, dysarthria and/or oculomotor disorder, due to cerebellar degeneration in the absence of coexisting diseases. "SCA15 is a degenerative, adult‐onset autosomal dominant cerebellar ataxia, primarily caused by deletions in the ITPR1 gene." (PMID 41325768, 2025). "The molecular and clinical characteristics of ITPR1-associated autosomal dominant cerebellar ataxias in the literature." (PMID 29186133, 2017). "SCA15 is an adult-onset disease that presents with autosomal dominant cerebellar ataxia and attendant gait impairment due to heterozygous deletions spanning the ITPR1 locus." (PMID 31658749, 2019).
bladder cancer (6 papers, 2016 to 2022). "From our work in this research, we demonstrated the oncogenic role of ITPR3 in bladder cancer in contrast to the roles of ITPR1 and ITPR2, whose proapoptotic effect was already described." (PMID 33573671, 2021). "In bladder cancer, the overexpression of ITPR1 in drug-resistant cells could induce cell apoptosis and increase sensitivity to cisplatin." (PMID 35313846, 2022). "We also found that ITPR1 was expressed at low levels in bladder cancer, while there was no obvious difference in ITPR2 expression compared with normal expression which was consistent with the result of western-blot." (PMID 33573671, 2021).
Obesity (6 papers, 2017 to 2023). Accumulation of substantial excess body fat. "Equally important, ITPR1 has been associated in different GWASs with diabetic kidney disease and obesity-related traits." (PMID 32290556, 2020). "Finally, in the Hispanic population, ITPR1 was associated to the pathophysiology of childhood obesity, while ITPR3 was linked to body mass index variants conferring a high risk of extreme obesity." (PMID 32290556, 2020).
aniridia (5 papers, 2016 to 2024). Aniridia is a congenital ocular malformation characterized by the complete or partial absence of the iris. "Additionally, a rare cause of aniridia is the Gillespie syndrome, which features partial aniridia, cerebellar ataxia, and intellectual disability, and is caused by recessive pathogenic variants in the ITPR1 gene." (PMID 34573386, 2021). "Most forms of aniridia are caused by pathogenic variants affecting PAX6, a highly conserved “master regulator” of eye development, localized to 11p13, with a small fraction of cases remaining unexplained or due to pathogenic variants in ITPR1, FOXC1, or PITX2." (PMID 34573386, 2021). "A separate cohort of 173 individuals with non-syndromic aniridia and with no mutation in PAX6 detected were screened for mutations in ITPR1 using the targeted resequencing amplicons." (PMID 27108798, 2016).
autism (5 papers, 2013 to 2023). Persistent deficits in social interaction and communication and interaction as well as a markedly restricted repertoire of activity and interest as well as repetitive patterns of behavior. "Another CNV study of 1,124 families, each of which included a single proband, his/her unaffected parents and, in most cases, an unaffected sibling, revealed as many as 234 CNV regions in several genes, including ITPR1, to be associated with autism." (PMID 23697635, 2013). "They found regions in chromosome 3p25.3, where ITPR1 is located, significantly enriched in individuals with autism." (PMID 23697635, 2013). "With respect to ASD, transcriptomic analysis of frontal and temporal cortex tissues from 16 individuals with autism and 16 controls revealed down-regulation of ITPR1." (PMID 23697635, 2013). "In addition, a study on autism risk genes in probands from the Autism Clinical and Genetic Resources in China (ACGC) identified one maternally and one paternally inherited missense variant of ITPR1, and another variant is found in patients with NDDs." (PMID 32244264, 2020). "However, considering the role of purine metabolic disorders in autism, role for CNTN4 and ITPR1 in the regulation of SUA seems plausible and needs to be evaluated further." (PMID 27039371, 2016).
Dystonia (5 papers, 2013 to 2022). An abnormally increased muscular tone that causes fixed abnormal postures. "In fact, virtually all genes associated with dystonia in spontaneous mutants (tottering, stargazer, ophisthotonus, ducky, lethargic, waddles, and wriggle) are involved in Purkinje cell Ca2+ signaling (Canca1a, Cacng2, Itpr1, Cacna2d2, Cacnb4, and Pmca2)." (PMID 29770609, 2018).
epilepsy (5 papers, 2012 to 2023). A brain disorder characterized by episodes of abnormally increased neuronal discharge resulting in transient episodes of sensory or motor neurological dysfunction, or psychic dysfunction. "Lack of family history suggests a de novo pathology, albeit her mother has history of epilepsy, but clinical genetic testing yielded no candidate variants, as a single ITPR1 VUS was found." (PMID 38239855, 2023).